LINC00336 (long independently transcribed non-coding RNA 336)
Synonyms: C6orf227; NCRNA00336; FLJ43752
Gene: Long non-coding RNA gene on chromosome 6 (33,586,099 to 33,593,467, reverse strand). Ensembl gene ENSG00000197251.
Diseases named in the same sentence as LINC00336 in open-access papers:
LINC00336 is named in the same sentence as 4 diseases in open-access papers, as found by Europe PMC text mining. Sharing a sentence is not in itself a finding about the gene and the disease. The quoted sentences say what the papers report.
lung carcinoma (21 papers, 2019 to 2025). "LINC00336 was reported to inhibit ferroptosis in lung cancer cells by acting as a sponge for miR-6852 and positively regulating its target, CBS (cystathionine β-synthase)." (PMID 38534739, 2024). "The gene LINC00336 is upregulated and acts as a competing endogenous RNA (ceRNA) oncogene in lung cancer, which suppresses ferritin formation." (PMID 36830675, 2023). "LINC00336 functions as an oncogene in lung cancer and regulates cystathionine-β-synthase (CBS) expression by competing for miR6852." (PMID 35223846, 2022). "For example, upregulation of the lncRNA, LINC00336, in lung cancer cells has been shown to activate the LSH/ELAVL1/LINC00336 axis, resulting in inhibition of ferroptosis and increased tumor formation." (PMID 35359880, 2022). "The LINC00336 gene suppresses ferroptosis in lung cancer by functioning as a competing endogenous RNA." (PMID 34395526, 2021). "LINC00336 was found to be upregulated in lung cancer and acts as a competitive endogenous RNA to inhibit ferroptosis in lung cancer to induce tumor formation." (PMID 34616431, 2021). "It is unveiled that LINC00336 accelerated tumor formation and inhibited ferroptosis of lung cancer through the LSH/ELAVL1/LINC00336 axis." (PMID 35127813, 2021). "First, the researchers used RSL3 (a ferroptosis activator) to treat A549 and SPC-A-1 lung cancer cells and observed that LINC00336 overexpression limits RSL3-induced cellular ferroptosis." (PMID 33558499, 2021). "In situ hybridization results showed that LINC00336 was localized primarily in the nucleus of lung cancer tissues, and that LINC00336 levels significantly increased in both lung ADC and SCC." (PMID 30787392, 2019). "To further uncover the physiological role of LINC00336 in lung cancer, we performed the stable knockdown of LINC00336 in PC9 cells." (PMID 30787392, 2019). "Connected with the upregulation of LINC00336, it performs a vital function in lung cancer." (PMID 35276059, 2022). "Given that ELAVL1 binds to many mRNAs, and that LINC00336 is highly expressed in lung cancer, we hypothesized that ELAVL1 may influence the posttranscriptional levels of interacting genes, including LINC00336." (PMID 30787392, 2019). "In addition, overexpressed LINC00336 acted as a crucial ferroptosis inhibitor in lung cancer by lowering cellular iron, lipid peroxidation, and mitochondrial superoxide through ELAV-like RNA-binding protein 1 (ELAVL1) interactivity, a novel regulator of ferroptosis." (PMID 35813823, 2022). "Moreover, ELAVL1 directly stabilizes LINC00336 in lung cancer cells." (PMID 35382824, 2022). "In addition, lncRNAs such as DANCR, LINC00336, MNX1-AS1, LINC00673, SNHG4, LEF1-AS1, UCA1 (urothelial carcinoma-associated 1), SNHG1, and PTAR act as ceRNAs for miRNAs and exhibit oncogenic functions in lung cancer cells." (PMID 33412752, 2020). "Finally, we further analyzed the correlation between ELAVL1 and LINC00336 in lung cancer." (PMID 30787392, 2019). "To address whether LINC00336 has a role in lung cancer in vivo, we used a xenograft model." (PMID 30787392, 2019). "To address whether LINC00336 also has a role in lung cancer in vivo, we used a xenograft model." (PMID 30787392, 2019). "ELAVL1 enhances the expression level of LINC00336 by interacting with LINC00336 (Long noncoding RNA), increases the expression of CBS (cystathionine-β-synthase) and inhibits ferroptosis in lung cancer." (PMID 34977044, 2021).
lung carcinoma (continued). "Finally, we found patients who had relatively higher levels of LINC00336 are associated with poor overall survival from lung cancers; this was assessed through a Kaplan–Meier analysis of a cohort of patients with lung cancer, indicating that LINC00336 might be used as a biomarker of NSCLC." (PMID 30787392, 2019). "LINC00336 also served as an endogenous sponge of MIR6852 as a circulating extracellular DNA (ceRNA) to increase cystathionine-β synthase (CBS) expression and inhibit ferroptosis in lung cancer." (PMID 35813823, 2022). "The lncRNA LINC00336 may increase the growth of lung cancer cells through the LSH/ELAVL1/LINC00336 axis, accelerate tumor formation, and inhibit ferroptosis pathways in lung cancer cells." (PMID 35756659, 2022). "We also examined whether ectopic LSH alters LINC00336 expression, as the overexpression of LSH in lung cancer cells significantly affected LINC00336 expression." (PMID 30787392, 2019).
tumor (8 papers, 2019 to 2022). "Together, our results demonstrate that LINC00336 is linked to cell growth, colonization, tumor growth, and ferroptosis, suggesting that LINC00336 performs a critical oncogenic function in cancer progression." (PMID 30787392, 2019). "Together, our results demonstrate that LINC00336 overexpression is linked to cell growth, colonization, and tumor growth, suggesting that LINC00336 performs a critical oncogenic function in cancer progression." (PMID 30787392, 2019). "LINC00336 acts as an oncogene that promotes tumor cell proliferation, inhibits ferroptosis, and induces tumor formation in an ELAVL1-dependent manner." (PMID 36105219, 2022). "We injected PC9 cells into nude mice and observed that LINC00336 depletion significantly impaired tumor size, volume, and weight; however, body weights did not change significantly in either group." (PMID 30787392, 2019). "In summary, our study illustrates that LINC00336 functions as an oncogene to facilitate tumor cell proliferation, inhibit ferroptosis, and induce tumor formation in an ELAVL1-dependent manner." (PMID 30787392, 2019). "The injection of A549-LINC00336 and SPC-A-1-LINC00336 showed that LINC00336 overexpression significantly increased tumor sizes, volumes, and weights after 1 month of growth compared with A549-Vector and SPC-A-1-Vector cells, whereas the whole-body weight remained unchanged." (PMID 30787392, 2019).
cancer (1 paper, 2019). A tumor composed of atypical neoplastic, often pleomorphic cells that invade other tissues. "Here we present strong evidence showing that LINC00336 is silenced by MIR6852 in cancer cells." (PMID 30787392, 2019).
lung (1 paper, 2019). "We found that LINC00336 was upregulated in both lung ADC and SCC primary tumors." (PMID 30787392, 2019).